TYRP1 (tyrosinase related protein 1)
Diseases named in the same sentence as TYRP1 in open-access papers (continued):
Sharing a sentence is not in itself a finding about the gene and the disease.
melanoma (continued). "TYRP1 expression was MITF-M-independent, since in all BRAFV600E melanoma cell lines, both MITF-Mhigh and MITF-Mlow, levels of TYRP1 transcript were similar." (PMID 31624899, 2020). "A significant correlation between TYRP1 mRNA level and MITF level was found also in a subset of melanoma cell lines." (PMID 31624899, 2020). "Next, we tested if the 36 active compounds from the IFNγ HTRF assay and the cell viability assay can affect expression of genes that regulate melanoma cells differentiation and pigmentation such as MITF, DCT, Melan-A and Tyrosinase-related protein 1(Tyrp)." (PMID 32231230, 2020). "The FUBRS likely reduced melanogenesis by inhibiting tyrosinase activity and the expression levels of tyrosinase, TYRP1, and TYRP2 via inhibiting expression of MITF in B16F10 melanoma cells." (PMID 32423183, 2020). "Consistent with the ChIP-seq data showing overlapping peaks in human melanocytes and melanoma cells, we found that both BRD4 and BRD2 were bound to the Tyr and Tyrp1 promoters in Melb-a cells and that (+)JQ1 disrupted binding." (PMID 32151278, 2020). "In human melanoma cell lines, melanoma antigens gp100, MART1, TYRP1, and TYRP2 were upregulated at the mRNA level following treatment with HDAC6 inhibitors (Nexturastat A or Tubastatin A)." (PMID 30176876, 2018). "Correspondingly, we show that 17-AAG and cellular immunotherapy directed against Tyrp1 are synergistic; revealing a new mechanism whereby 17-AAG can potentiate the effects of an established melanoma therapy." (PMID 29481571, 2018). "Disruption of VEGF/VEGFR-2 signaling by simultaneous transfer of CAR T cells expressing anti-VEGFR-2 and T cells specific for gp100 (PMEL), TRP-1 (TYRP1), or TRP-2 (DCT) significantly eradicated B16 melanoma tumors in mice." (PMID 29682521, 2018). "Adoptive transfer of in vitro polarized tumor antigen-specific (tyrosinase-related protein 1, TRP-1) Th17 cells into B16 melanoma tumor bearing mice demonstrated that Th17 cells were more potent to induce tumor rejection compared to Th1 cells." (PMID 26583099, 2015). "We therefore examined the expression of melanoma-specific differentiation genes including Melan-A (MLANA), Tyrosinase (TYR) and Tyrosinase-related protein 1 (TYRP1) by quantitative PCR." (PMID 24406338, 2014). "Among the downregulated genes were TYRP1 (tyrosinase-related protein 1) and ABCB5 (ATP-binding cassette, sub-family B, member 5), both of which are related to melanoma progression and initiation." (PMID 23056502, 2012). "Thus, TYRP1 could emerge as a valuable prognostic marker, especially in melanoma patients where important prognostic factors at diagnosis cannot be evaluated (namely unknown or ulcerated primaries) and in metastases of thin melanomas." (PMID 22045183, 2011). "In neural crest, melanocyte, and melanoma cells, PAX3 was found to regulate MITF, NGN2, RET, SOSTDC1, MSX2, DCT, and TYRP1 genes, as well as genes expressed ubiquitously or widely (and including melanocytes), such as BCL-XL, CXCR4, FGFR4, HES1, MET, NF1, TGFb2, and WNT1." (PMID 40428399, 2025). "These include validated melanoma targets, such as CXCR4, MET and TYRP1." (PMID 40428399, 2025). "However, melanoma cells and normal melanocytes share common antigens (MART-1/Melan A, gp100, tyrosinase-related protein 1, 2)." (PMID 40861456, 2025). "We here demonstrate that tyrosinase (but not Tyrp-1) in B16 melanoma cells undergoes ubiquitination and subsequent degradation in lysosomes." (PMID 38392670, 2024). "This clinical study made use of an ‘active drug’ PK assay measuring the concentration of drug able to bind both TYRP1 and CD3 proteins simultaneously, and therefore capable of promoting synapse formation between TYRP1-expressing melanoma cells and CD3+ T cells." (PMID 38577337, 2024). "Inhibition of differentiation during the progression of CD133-expressing melanoma stem cells may therefore be mediated by downregulation of RARB, TYRP1, and TYRP2, among other mechanisms." (PMID 38727313, 2024).
melanoma (continued). "Our results show that all constructs lead to target cell killing and interferon-gamma (IFNγ) release upon co-culture with melanoma cells with high expression of total TYRP1 but not when co-cultured with cells with intermediate expression." (PMID 38336975, 2024). "Although WRN and TYRP1 genes and their variations were correlated with different types of cancer, including melanoma, the currently identified WRN and TYRP1 variants were not reported previously in melanoma cases." (PMID 38028607, 2023). "However, we noted that while MITF expression was similar in primary tumors and metastases, a number of well‐characterized MITF target genes (e.g., TYR, TYRP1, MELANA, PMEL) were significantly more highly expressed in primary melanomas than in metastases." (PMID 35771179, 2022). "Although it has a specific function in melanogenesis, it seems that high expression profiles of TYRP1 are not exclusive to melanoma." (PMID 36241983, 2022). "On the contrary, human tyrosinase related protein 1 (TYRP1) is a melanosome protein involved in the pigmentary machinery of melanocytes and well-studied for its emerging roles in the malignant melanocyte and melanoma progression." (PMID 35345444, 2022). "Melanoma is a highly malignant tumor derived from melanocytes, which differentiate via melanogenesis regulated by melanocortin 1 receptor (MC1R), tyrosinase (TYR), TYR-related protein-1 (TYRP1), and dopachrome tautomerase (DCT)." (PMID 35619714, 2022). "Additionally, both tyrosinase agonist 2-ETZ and tyrosinase substrate L-tyrosine significantly increased MITF, Tyrosinase, TYRP1 and TYRP2 expression and tyrosinase activity in parental B16 melanoma cells." (PMID 35265199, 2022). "Notably, a fully human anti-TYRP1 monoclonal antibody (20D7) that induced strong ADCC and suppressed human and mouse melanoma growth in subcutaneous and metastatic models in immunocompromised mice was described in the literature." (PMID 33520112, 2021). "A ‘sponge’ activity of TYRP1 transcript in melanoma cells resistant to BRAFV600E and MEK1/2 inhibitors was not considered until now." (PMID 31624899, 2020). "For example, the immunogenic noncHLAIp derived from the dORF in the ABCB5 gene was moderately expressed in only 37% of the melanoma cells compared to the expression of the TYR and TYRP1 genes, both of which were highly and uniformly expressed and produced confirmed immunogenic epitopes." (PMID 32157095, 2020). "This analysis confirms stable expression of TYRP1 in melanoma cells irrespective of their sensitivity to BRAFV600 and MEK1/2 inhibitors." (PMID 31624899, 2020). "Since TYR and TYRP1 are MITF target genes, we interrogated previously published ChIP-seq datasets to determine if BRD4 and MITF co-occupy MITF-binding sites at the TYR and TYRP1 loci in melanocytes and melanoma cells." (PMID 32151278, 2020). "Our results are contradictory to these findings as: (i) TYRP1 expression was similar in MITF-Mlow and MITF-Mhigh melanoma cells and (ii) MITF-M loss accompanying the development of drug resistance in MITF-Mhigh cells, did not influence TYRP1 expression." (PMID 31624899, 2020). "Here the 17-AAG dependent, tyrosinase-independent induction of melanin formation in human SK-Mel-30 melanoma cells implicates DCT and TYRP1 in facultative melanization, showing that these accessory melanogenic enzymes can modulate pigmentation without changes in tyrosinase." (PMID 29481571, 2018). "Since we observed a close correlation between the Wnt3a-CM or PKF115–584 treatment and the expression of pigmentation related genes (DCT, TYR, TYRP1, MITF) in our SKMEL28 microarray data, we analyzed the TCGA melanoma RNAseq expression data concerning MLANA expression." (PMID 29454361, 2018). "On the contrary, upregulation of TYRP1, CNTN1 and UCHL1 in melanoma could be reversing malignant conditions." (PMID 27206673, 2016).
melanoma (continued). "Finally, this work allowed proposing TYRP1, cofilin-1 and CAP1 as potential markers to detect melanomas with varying degrees of aggressiveness." (PMID 27206672, 2016). "Thus, we found down-regulation of the TYRP1 gene, a melanocyte differentiation marker and over expression of MFI2 gene, a cell-surface glycoprotein playing a role in melanoma cell proliferation and tumorigenesis and EEA1 gene, a marker of early endosomes." (PMID 24742402, 2014). "When human melanoma MNT-1 cells and melanocytes were treated with sucrose, we observed the decreased melanin content, the reduced merged expression of M6PR with TYRP-1 or PMEL17 and swollen vacuoles, implying that hyperosmotic stress disturbs the proper vesicle trafficking for melanosome formation." (PMID 25170965, 2014). "SK-MEL-19 cells express endogenous TYRP1, while this gene is not expressed in many other melanoma cell lines." (PMID 22457636, 2012). "Furthermore, our global gene analysis also showed the upregulation of the melanocyte-differentiation gene TYRP1 and master regulator of neural crest specification SNAI2 (Slug), which is also over- expressed in aggressive melanoma." (PMID 21526207, 2011). "It was found that the overall gene combination was related to the melanoma distinction (Wilks Lambda = .057, p < .001) with the standardized canonical discriminant function coefficients being MART1 = .267, TYR = .420, TYRP1 = .361, TYRP2 = .595, and QPCT = .808." (PMID 16820060, 2006). "Furthermore, in B16-F10 melanoma cells, Mb-ME suppresses melanogenesis by reducing melanin secretion and cellular melanin content, although it does not directly affect tyrosinase activity or the expression of key melanogenic regulators such as MITF and TYRP1." (PMID 40076896, 2025). "In a syngeneic B16F0 melanoma model and using tyrosinase related protein 1 (TRP1) as a vaccine antigen, it has been found that simultaneous delivery of IL-12 and a PD-L1-silencing shRNA was the only combination that exhibited therapeutically relevant anti-melanoma activities." (PMID 37006306, 2023). "In addition, small interfering RNA-mediated MITF silencing in melanoma cells significantly reduces melanin content by inhibiting TYR, TYRP-1, and MC1R, which indicates that the transcriptional activation of MITF is a promising strategy for treating hypopigmentation." (PMID 36235048, 2022). "It was reported that tyrosol could inhibit TYRP-1 (rather than TYRP-2) expression in B16F0 mouse melanoma cells." (PMID 36290598, 2022). "In mouse melanoma B16F10 cells, this compound had multiple effects, including the upregulation of TYR and CD63 mRNA(s) and protein(s), without affecting the levels of the melanogenic master transcriptional regulator microphthalmia transcription factor (MITF) or TYRP-1 mRNA(s)." (PMID 35011407, 2021). "Interestingly, our results are consonant with an earlier study showing lack of significant changes in TYRP1 expression upon Mitf-transfection of Mitflow SK-MEL-28 melanoma cells." (PMID 31624899, 2020). "Additionally, we reported a GH-induced upregulation and GHRKD-induced suppression of MITF-regulated melanogenesis pathway genes—TYR, TYRP1, TYRP2/DCT—as well as melanosomal markers PMEL (gp100) and MLANA, in multiple melanoma cell lines, xenograft models, and in silico analyses." (PMID 31547367, 2019). "Based on the analysis performed on patient biopsies, we anticipate that ~30% of all melanoma patients without response or with relapse after ICB therapy will express high levels of TYRP1 and will be eligible for the TYRP1 CAR-T cell clinical trial." (PMID 38336975, 2024). "The top final variants and their corresponding genes most relevant to hereditary cancers and melanoma and present in both the patient and the sibling with a brain tumor, but not in the control, are in WRN, TYRP1, and ERCC2, shown in and discussed as follows." (PMID 38028607, 2023).
melanoma (continued). "TYRP1 transcript levels, which were almost the same in drug-naïve, vemurafenib-resistant and on-drug-holiday BRAFV600E melanoma cells, were not markedly altered also in cells only shortly exposed to vemurafenib." (PMID 31624899, 2020). "Surprisingly, 17-AAG also stimulated melanin production in SK-Mel-30 cells and enhanced TYRP1 and DCT expression without stimulating TYR production in all three BRAFWT cell lines studied as well as in B16F10 mouse melanoma cells." (PMID 29481571, 2018). "However, 17-AAG, in combination with and without PLX4032, increased the expression of DCT and TYRP1, but not TYR, in all 3/3 BRAFWT melanoma cell lines." (PMID 29481571, 2018).
albinism (24 papers, 2005 to 2025). A congenital disorder characterized by partial or complete absence of melanin pigment in the eyes, hair, or skin. "TYRP1 encodes the melanosomal enzyme tyrosinase-related protein 1, and mutations in this gene can cause albinism and confer increased risk for familial cutaneous melanoma." (PMID 33318654, 2020). "The OCA3 and the OCA4 phenotypes of albinism are caused by mutations in genes encoding tyrosinase related protein 1 (TRP1) and membrane associated transport protein (MATP), respectively." (PMID 26347819, 2015). "Previous studies have suggested that albinism-associated mutations may disrupt TYRP1 catalytic activity, interactions between TYRP1 and TYR, or intracellular transport of TYRP1." (PMID 37522525, 2023). "The third type of albinism, OCA3 (MIM 203290), is associated with TYRP1 mutations (MIM# 115501)." (PMID 35741834, 2022). "However, sequence analysis revealed a homozygous missense (c.1579G>C, p.(Glu527Gln)) variant in TYRP1 consistent with albinism." (PMID 28378818, 2017). "Additionally, these residues are found in a spatial region that contains a large number of known albinism-associated human mutations, suggesting that this region of the TYRP1 protein may be easily disrupted by mutations." (PMID 37522525, 2023). "Molecular genetic diagnosis for most patients started with a next-generation sequencing (NGS) panel targeting genes associated with albinism—TYR, OCA2, MC1R, MITF, SLC45A2, TYRP1, and GPR143—as the initial clinical diagnosis for all patients was albinism." (PMID 39457042, 2024). "Molecular studies identified seven genes linked to the OCA phenotype (TYR, OCA2, TYRP1, SLC45A2, SLC24A5, C10orf11, and DCT) and one locus (OCA5) in consanguineous and sporadic albinism." (PMID 35741834, 2022). "The OCA3 and OCA4 phenotypes of albinism are caused by mutations in genes encoding tyrosinase-related protein 1 (TYRP1) and membrane-associated transporter protein (MATP), respectively." (PMID 31777350, 2019). "Our findings suggest that albinism in P. pingi is synergistically driven by hyperactivation of ubiquitin-mediated proteolysis (which suppressed TYR/TYRP1 enzymatic activity and disrupted the pH homeostasis of melanosomes), and inhibition of calcium signaling (which impeded melanin transport)." (PMID 41227331, 2025). "Computational methods have also been used to investigate the effect of mutations on enzyme–ligand interactions; Kamaraj and Purohit studied Tyrp1 mutant variants R326H and R356Q, associated with OCA3 albinism, using MD simulations to understand structural consequences." (PMID 38542347, 2024). "Other albinism classes are: OCA2 caused by deletion or loss of activity of the melanosomal P-protein (OCA2 gene); OCA3 attributable to mutations in TYRP1; OCA4 due to loss of SLC45A2; and OCA5 which is linked to chromosome 4q24, with the responsible gene yet to be characterized." (PMID 32966289, 2020). "Several of the ciliary body/iris signature genes were noteworthy in that their mutation can lead to albinism or hypopigmentation phenotypes, including OA1 (ocular albinism type 1), TYR and TYRP1 (oculocutaneous albinism 1A and 3, respectively), and MLPH (Griscelli syndrome)." (PMID 16168081, 2005). "In addition to ASIP, IRF4, KITLG, MC1R, SLC24A4, and TYRP1, we chose 41 additional candidate genes with a potential role in human skin color based on their phenotypes in model organisms, or in humans affected with albinism." (PMID 23555287, 2013). "As the major enzymes participated in mammals albinism, TYR, TYRP1, OCA2 and SLC45A2 also exhibited down regulation in albino pigmented P. olivaceus individuals." (PMID 28777813, 2017). "Genetic analysis revealed seven coding variants in the cohort that were presumed to be albinism-causing and, to the authors’ knowledge, have not previously been reported: three in TYR, one in OCA2, one in TYRP1, one in SLC45A2, and one in GPR143." (PMID 38441889, 2024).
albinism (continued). "The most common cause of foveal hypoplasia is albinism, but no mutations were identified in SLC45A2, TYR, TYRP1, GPR143, OCA1, OCA2, OCA3, or OCA4." (PMID 28546991, 2017).